E2F3 (E2F transcription factor 3)
Diseases named in the same sentence as E2F3 in open-access papers (continued):
Sharing a sentence is not in itself a finding about the gene and the disease.
glioblastoma (11 papers, 2011 to 2022). The most malignant astrocytic tumor (WHO grade IV). "Pik3r1 and E2f3 were associated with all three glioblastoma survival variables." (PMID 21649900, 2011). "The oncogenic roles of HELLS in glioblastoma are likely mediated through interactions with E2F3 and MYC." (PMID 34315468, 2021). "E2F3 was also identified as a functional downstream target of miR-195 via robust arrested cell cycle progression in glioblastoma cells." (PMID 28947999, 2017). "In human glioblastoma cells, miR-195 was testified to function as a tumor suppressor by targeting E2F3." (PMID 28947999, 2017). "Taken together, these data indicate that miR128-1 directly targets BMI1 and E2F3 in glioblastoma cells." (PMID 27705931, 2016). "Likewise, a link between E2f3 and glioblastoma has been reported." (PMID 21649900, 2011). "Both E2F3a and E2F3b were found to interact with HELLS, thereby increasing the expression of cell cycle progression-related genes to maintain glioblastoma CSC proliferation, while proliferation was impaired after E2F3 gene knockdown." (PMID 34476219, 2021). "To confirm miR128-1 targeting of BMI1 and E2F3 in glioblastoma cells, we measured BMI1 and E2F3 expression in U251 and U87 cells after miR128-1 transfection." (PMID 27705931, 2016). "Furthermore, we showed that miR128-1 targeted BMI1 and E2F3, and miR128-1 overexpression down-regulated BMI1 and E2F3 in glioblastoma cells both in vitro and in mouse tumor xenografts." (PMID 27705931, 2016). "Compared with LGG, except for E2F3 and E2F5, all E2Fs were highly expressed in HGG samples and correlated with grade progression, with highest expression attributed to glioblastoma (GBM, grade IV)." (PMID 32064771, 2020).
neuroblastoma (11 papers, 2007 to 2025). Neuroblastoma (NB) is the most common solid, extracranial childhood tumor. "The higher expression levels of E2F3 were associated with the worse clinical outcomes of stage 4S neuroblastoma." (PMID 35764946, 2022). "Genes associated with E2F1 and E2F3 expressions in neuroblastoma were significantly enriched in cell cycle signaling pathway." (PMID 35764946, 2022). "We then constructed a risk model based on E2F1, E2F3 expression features and age of diagnosis to predict the clinical overall survival of pediatric neuroblastoma." (PMID 35764946, 2022). "Identification of 234 genes were associated with E2F1 and E2F3 expressions in neuroblastoma and those genes were significantly enriched in cell cycle signaling pathway." (PMID 35764946, 2022). "miR-34a acts as a suppressor of neuroblastoma tumorigenesis by targeting the mRNA encoding E2F3 and reducing E2F3 protein levels." (PMID 17894887, 2007). "Furthermore, E2F1 and E2F3 were both significantly associated with the overall survival of neuroblastoma in TARGET, GSE16476, GSE85047 and E-MTAB-1781 datasets." (PMID 35764946, 2022). "Moreover, E2F3 was associated with the overall survival of neuroblastoma in TARGET, GSE16476, GSE85047 and E-MTAB-1781 datasets." (PMID 35764946, 2022). "Higher expression levels of E2F1 or E2F3 were associated with the worse prognosis of neuroblastoma." (PMID 35764946, 2022). "Moreover, the expression levels of E2F1 and E2F3 were positively correlated with the risk score in pediatric neuroblastoma patients." (PMID 35764946, 2022). "We then assessed the associations of age of diagnosis, MYCN amplification and E2F1 expression and E2F3 expression in the prediction of the overall survival of neuroblastoma using multivariable cox regression assay." (PMID 35764946, 2022). "E2F transcription factors E2F1, E2F3, E2F7 and E2F8 were all associated with the event free survival of neuroblastoma in TARGET, GSE16476 and GSE85047 datasets." (PMID 35764946, 2022). "Combined the univariable cox regression assay in four independent datasets, E2F1 and E2F3 were most significantly correlated with the event free survival and overall survival of neuroblastoma." (PMID 35764946, 2022). "Combinations of E2F1, E2F3 with MYCN amplification or age of diagnosis achieved better prognosis of neuroblastoma." (PMID 35764946, 2022). "Results from both cox regression assay and Kaplan–Meier survival analysis suggested that E2F1 and E2F3 transcription factors were correlated with the event free survival and overall survival of neuroblastoma." (PMID 35764946, 2022). "Combinations of E2F1 expression, E2F3 expression with MYCN amplification or age of diagnosis achieved better prognosis of neuroblastoma." (PMID 35764946, 2022). "Compared with neuroblastoma patients with higher expression levels of E2F3, neuroblastoma patients with lower expression levels of E2F3 had significantly prolonged overall survival." (PMID 35764946, 2022). "Expression levels of E2F1 and E2F3 were higher in neuroblastoma patients with MYCN amplification or age at diagnosis ≥ 18 months." (PMID 35764946, 2022). "Combinations of E2F1 expression, E2F3 expression with MYCN amplification or age of diagnosis achieved better prognosis in neuroblastoma." (PMID 35764946, 2022). "Over-expressions of E2F1 or E2F3 were correlated with the shorted event free survival and overall survival of neuroblastoma." (PMID 35764946, 2022). "Compared with neuroblastoma patients with lower E2F3 expressions, 5202, 2690, 5284 and 6132 genes were significantly changed in neuroblastoma patients with higher E2F3 expressions in TARGET, GSE16476, GSE85047 and E-MTAB-1781 datasets, respectively." (PMID 35764946, 2022). "The expression levels of E2F1 and E2F3 were higher in neuroblastoma patients with MYCN amplification or age at diagnosis ≥ 18 months." (PMID 35764946, 2022).
neuroblastoma (continued). "On the contrary, pediatric neuroblastoma patients with age at diagnosis ≥ 18 months and with higher E2F3 expression levels had the worst clinical event free survival and overall survival than other sub-groups." (PMID 35764946, 2022). "In order to confirm this finding, we screened 38 paraffin-embedded tissue samples stage 4S neuroblastoma for E2F3 protein expression using immunofluorescence, and we observed that augmented expression was strongly associated with impaired event-free survival." (PMID 32429447, 2020). "Moreover, the mechanisms of E2F1 and E2F3 in the regulations of metabolism signaling pathways in neuroblastoma should be further studied." (PMID 35764946, 2022). "Furthermore, in TARGET, GSE85047 and E-MTAB-1781 datasets, the expression levels of E2F3 were also higher in neuroblastoma patients with age at diagnosis ≥ 18 months than neuroblastoma patients with age at diagnosis < 18 months." (PMID 35764946, 2022). "Therefore, functions of E2F1 and E2F3 should be further studied in neuroblastoma cells by using in vivo or in vitro experiments." (PMID 35764946, 2022). "Similarly with E2F1, E2F3 was also additively predicted the clinical overall survival of neuroblastoma with MYCN amplification or age of diagnosis." (PMID 35764946, 2022). "The abnormal expressions of E2F1 and E2F3 may confer the uncontrolled cell cycle and DNA replication in neuroblastoma." (PMID 35764946, 2022). "Furthermore, E2F1 and E2F3 also shared similar downstream transcriptional features in pediatric neuroblastoma." (PMID 35764946, 2022). "E2F transcription factors E2F1 and E2F3 were prognostic makers of neuroblastoma." (PMID 35764946, 2022). "Furthermore, pediatric neuroblastoma patients with age at diagnosis < 18 months and with lower E2F3 expression levels had the best clinical event free survival and overall survival than other sub-groups in TARGET, GSE16476, GSE85047 and E-MTAB-1781 datasets." (PMID 35764946, 2022). "E2F1 and E2F3 were prognostic factors in all four independent pediatric neuroblastoma cohorts." (PMID 35764946, 2022). "We have interrogated in silicopublic neuroblastoma databases for regulators involved in the RB-E2F pathway especially for E2F factors themselves, and we identified the E2F transcription factor 3 (E2F3) expression as a potential prognostic marker in stage 4S neuroblastoma." (PMID 32429447, 2020). "Furthermore, it was previously reported that the overexpression of miR-34a led to the growth arrest and apoptosis in neuroblastoma cells by silencing the expression of E2f3." (PMID 22454691, 2012). "Moreover, E2F1 and E2F3 were independent neuroblastoma prognostic factors." (PMID 35764946, 2022). "Also, E2F1 and E2F3 were associated with MYCN amplification and age of neuroblastoma diagnosis." (PMID 35764946, 2022). "In the further development of therapeutic strategies of neuroblastoma by targeting on E2F transcription factors, E2F1 and E2F3 should be simultaneously inhibited to achieve better clinical outcomes." (PMID 35764946, 2022). "In this study, using four neuroblastoma datasets, we showed that, compared with other E2F factors, E2F1 and E2F3 shared similar expressions and prognosis in pediatric neuroblastoma." (PMID 35764946, 2022). "We also determined the relationships of E2F3 expression, MYCN amplification and age of diagnosis in neuroblastoma patients." (PMID 35764946, 2022). "Follow-up studies suggested that miR-34a could function as a tumor suppressor in Neuroblastoma (NB) tumorgenesis by directly binding to E2F3 mRNA." (PMID 28947999, 2017). "In this paper, we highlighted that E2F1 and E2F3 were prognostic makers of neuroblastoma independent of MYCN amplification and age of diagnosis." (PMID 35764946, 2022). "Neuroblastoma patients with higher expression levels of E2F3 were also had lower event free survival in TARGET, GSE16476, GSE85047 and E-MTAB-1781 datasets, compared with neuroblastoma patients with lower expression levels of E2F3." (PMID 35764946, 2022).
neuroblastoma (continued). "E2F1 and E2F3 were prognostic factors in neuroblastoma, independent of MYCN amplification and age of diagnosis." (PMID 35764946, 2022). "Our results suggested that E2F1 and E2F3 were prognostic makers of neuroblastoma independent of MYCN amplification and age of diagnosis." (PMID 35764946, 2022). "E2F3 was also a prognostic maker of neuroblastoma independent of MYCN amplification, age of diagnosis and E2F1 expression in E-MTAB-1781 datasets." (PMID 35764946, 2022). "Also, most of the genes were highly expressed in neuroblastoma patients with higher E2F1 and E2F3 expressions." (PMID 35764946, 2022). "Additionally, Moqidem suggested that cell death induced by A. vulgaris on SH-SY5Y human neuroblastoma cell line was through apoptosis induction accompanied by significant downregulation of the cell cycle genes (CDK4, CDK6 and E2F3), and upregulation of the tumor suppressor gene PTEN." (PMID 36015443, 2022). "Moreover, the prognostic significance of E2F1 or E2F3 in neuroblastoma was independent of MYCN amplification and age of diagnosis." (PMID 35764946, 2022). "miRNA appeared to be downregulated in neuroblastoma cell lines due to promoter methylation, but treatments with 5′azacitidine increased miRNA expression and led to malignancy decrease through downregulation of miRNAs’ targets such as CDK6, DNMT3B, E2F3, OLFM3, and IFNAR1." (PMID 34832966, 2021). "Since, E2F1 and E2F3 were prognostic makers of neuroblastoma independent of MYCN amplification and age of diagnosis, the combinations of E2F1 or E2F3 with MYCN amplification or age of diagnosis could achieve better prognostic effects in pediatric neuroblastoma patients." (PMID 35764946, 2022). "E2F3 expression levels were higher in MYCN amplified neuroblastoma patients in TARGET, GSE16476, GSE85047 and E-MTAB-1781 datasets, compared with neuroblastoma patients without MYCN amplification." (PMID 35764946, 2022). "Pediatric neuroblastoma patients without MYCN amplification and with lower E2F3 expression levels had significantly longer event free survival and overall survival in GSE16476, GSE85047 and E-MTAB-1781 datasets." (PMID 35764946, 2022). "Moreover, E2F1 was a prognostic maker of neuroblastoma independent of MYCN amplification, age of diagnosis and E2F3 expression in TARGET, GSE85047 and E-MTAB-1781 datasets." (PMID 35764946, 2022).
cervical cancer (9 papers, 2019 to 2024). A primary or metastatic malignant neoplasm involving the cervix. "In cervical cancer, circ-E2F3 inhibits miR-296-5p increasing STAT3 nuclear translocation and upregulates expression of cyclin D1." (PMID 35444695, 2022).
nasopharyngeal carcinoma (9 papers, 2017 to 2023). A carcinoma arising from the nasopharyngeal epithelium. "Circular RNA CDR1as enhanced E2F3 stability and promoted the growth of nasopharyngeal carcinoma by sponging miR-7-5p." (PMID 34082777, 2021). "For example, Xist was highly expressed in nasopharyngeal carcinoma (NPC) and promoted tumor NPC cell growth in vitro and in vivo through miR-34a-5p-E2F3 axis." (PMID 29254174, 2017). "The ceRNA activity of XIST versus miR-34a has an oncogenic effect in two different tumors, thyroid cancer and nasopharyngeal carcinoma, due to de-repression of different targets in different cell contexts, i.e., MET and E2F3, respectively." (PMID 35054794, 2022). "E2F3 and CCNG1 was identified as targets of miR-203 in nasopharyngeal carcinoma (NPC), while latent membrane protein 1 (LMP1) was responsible for downregulation of miR-203." (PMID 28947999, 2017). "This work studies the impacts and mechanism of E2F transcription factor 3 (E2F3) in the growth and tumor microenvironment (TME) of nasopharyngeal carcinoma (NPC)." (PMID 37647439, 2023).
liver cancer (8 papers, 2019 to 2025). An epithelial or non-epithelial malignant neoplasm that arises from the liver. "It was found that rtcisE2F acts as a scaffold to promote the interaction between IGF2BP2 and E2F6/E2F3 mRNAs, thereby maintaining their stability and driving the self-renewal of liver cancer cells." (PMID 41155268, 2025). "Targeting components of the rtcisE2F–IGF2BP2/YTHDF2–E2F6/E2F3 axis may therefore represent a potential strategy for liver cancer therapy." (PMID 41155268, 2025). "By maintaining the stability of E2F transcription factor 6 (E2F6)/ E2F transcription factor 3 (E2F3), IGF2BP2 facilitates the stem cell self-renewal of liver cancer." (PMID 37554271, 2023). "microRNA-432-5p suppresses E2F3 translation by binding to the 3' UTR of E2F3, thereby influencing the invasion and migratory abilities of liver cancer cells." (PMID 37697333, 2023). "Activated E2F oncogenic signaling was always seen in the progression of liver cancer, and studies have shown that dosage-dependent copy number gains in E2F1 and E2F3 drive HCC." (PMID 31926109, 2020). "Similarly, in liver cancer, E2F1 and E2F3 were over-expressed, and synergistically induced the spontaneous development of liver cancer in mice." (PMID 35764946, 2022).
breast tumors (7 papers, 2008 to 2023). "E2F3 has been found to increase centrosome amplification in mammary epithelial cells and regulate breast tumor development and metastasis." (PMID 27459855, 2016). "Also, E2F1, E2F2, E2F3, Mps1/TTK, BubR1, NDC80 (HEC1), Nek2, and Sgo1 significantly co-overexpress in breast tumors." (PMID 29100415, 2017). "Observations that E2F1, E2F2, and E2F3 correlate with relapse-free but not overall survival was confirmed by mining the METABRIC database, a database that encompasses over 2000 breast tumors, with cBioPortal." (PMID 29100415, 2017).
diabetic nephropathy (7 papers, 2020 to 2025). "has-mir-770-5p can cause podocyte injury via targeting E2F3 in diabetic nephropathy." (PMID 35755170, 2022). "The downregulation of CDC25A, E2F3, and NFIB increases the risk of developing diabetic nephropathy." (PMID 40041782, 2025). "Inhibition of E2F3 expression promotes the development of diabetic nephropathy." (PMID 32235747, 2020). "Thus, the MIAT/miR-147a/E2F3 axis may promote cellular proliferation and fibrosis in the progression of diabetic nephropathy." (PMID 40282196, 2025).
bladder tumors (4 papers, 2010 to 2024). "It has been suggested that inactivation of Rb pathway and overexpression of E2F3 are obligate events in some human bladder tumors." (PMID 20421977, 2010). "For instance, the gain&CN-LOH hotspot #1, affecting E2F3 and SOX4, is the most frequent aberration in bladder tumors." (PMID 38473323, 2024).
COVID-19 (4 papers, 2022 to 2025). A disease caused by infection with severe acute respiratory syndrome coronavirus 2. "Upstream regulator analysis identified five key regulators after exposure to COVID-19 in our study, one phosphatase (PDCD1), 3 transcriptional regulators (E2F3, NUPR1 and LARP1) and one mitotic spindle protein (CKAP2L)." (PMID 35547542, 2022). "In our study, the KEGG analysis showed an interaction with E2F3, suggesting that the absence of low oxygen saturation in mild COVID-19 cases may account for the reduced expression of miR-210-3p." (PMID 40089674, 2025).
diabetes (4 papers, 2020 to 2023). "In contrast, loss of Cdk4 or skeletal muscle–specific deletion of Cdk4’s target, E2F3, depleted oxidative myofibers, deteriorated mitochondrial function, and reduced exercise capacity, while increasing diabetes susceptibility." (PMID 37395281, 2023). "Abundance of E2F3 contributed to insulin secreting β cell proliferation, providing promising alternative therapy for diabetes." (PMID 32348429, 2020). "For example, NKX6.1 is essential for both early and late stages of pancreatic development with a critical role in the formation of β cells, KLF14 is an important regulator of metabolic diseases, such as diabetes and obesity, and E2F3 activates β-cell proliferation." (PMID 36899442, 2023). "Muscle-specific E2F3-deficient mice are susceptible to HFD-induced obesity and diabetes." (PMID 37395281, 2023). "Using the vastus lateralis muscle biopsies from the 49 individual cohort, we next examined the correlation of E2F3 and PGC-1α mRNA expression levels with markers of adiposity, fitness level, and diabetes." (PMID 37395281, 2023).
osteoarthritis (4 papers, 2020 to 2023). A noninflammatory degenerative joint disease occurring chiefly in older persons, characterized by degeneration of the articular cartilage, hypertrophy of bone at the margins and changes in the synovial membrane. "It has been shown that GRB10 and E2F3 can be used as diagnostic markers of osteoarthritis, and they are important in the occurrence and development of this condition." (PMID 36960385, 2023). "In conclusion, GRB10 and E2F3 can be used as diagnostic markers of osteoarthritis, and immune cell infiltration plays an important role in the occurrence and progression of OA." (PMID 32235747, 2020). "In osteoarthritis, E2F3 is positively correlated with multiple immune cells, including resting mast cells, T regulatory cells, CD4 resting memory T cells and activated NK cells." (PMID 34741389, 2021).
brain tumors (3 papers, 2021 to 2023). "For example, Liao and colleagues reported that high E2F3 expression was linked to increased infiltration of lymphocytes, macrophages, neutrophils, and dendritic cells in brain tumors." (PMID 37647439, 2023).
clear cell renal cell carcinoma (3 papers, 2017 to 2023). "The E2F3 transcriptional regulatory pathway plays an important role in clear cell renal cell carcinoma (ccRCC)." (PMID 28986523, 2017). "The E2F3 transcriptional regulatory pathway plays a major part in multiple-cancer progression, but the specific contributions of this pathway to tumor formation and the progression of clear cell renal cell carcinoma (ccRCC) are not fully understood." (PMID 28903320, 2017).